SATB1 (SATB homeobox 1)
Diseases named in the same sentence as SATB1 in open-access papers (continued):
Sharing a sentence is not in itself a finding about the gene and the disease.
cancer (continued). "We have previously shown high expression of SATB1 in HCC could potentiate cancer cell with enhanced proliferating and metastatic ability." (PMID 27883059, 2016). "Special AT-rich binding protein 1 (SATB1) has been implicated in reprogramming chromatin organization and transcription profiles in many cancers and non-cancer-related conditions." (PMID 27883059, 2016). "However, SATB1 promotes cancer cell proliferation, anchorage-independent growth, migration and invasion in a manner that is dependent on the induction of c-Myc." (PMID 26701851, 2016). "Statistical analysis revealed that the SATB1 immunoreactivity was significantly higher in cancer cells of all the analyzed CRC cases as compared to its expression noted in cells of the unchanged mucosa (IRS 4.36 ± 0.38 vs. 1.74 ± 0.31, respectively; P < 0.0001)." (PMID 25874491, 2015). "Aberrant SATB1 expression could disrupt apoptosis by disturbing the balance between anti-apoptotic and pro-apoptotic genes, and thus contribute to cancer development." (PMID 26422397, 2015). "Further investigations combining 4C and high throughput techniques, such as ChIP-PET, to identify more SATB1-mediated mbr-promoter interactions and promoter-promoter interactions will provide new opportunities for clarifying how apoptosis is disrupted in cancer cells." (PMID 26422397, 2015). "In addition to nuclear SATB1 immunoreactivity, we also observed that SATB1 protein was present in the cytoplasm of cancer cells of 30.4 % studied CRC patients." (PMID 25874491, 2015). "Deregulation of SATB1 in malignant cells alone, in lieu of multiple successive genomic aberrations, is sufficient to alter the expression of a large number of genes required for the progression of cancer to metastasis." (PMID 25586771, 2015). "However, appropriate delivery vectors for siRNA or shRNA are important for SATB1 targeted cancer gene therapy." (PMID 24675979, 2014). "Positive SATB1-expression was observed in 20% of resected PB-type cases, and was associated with a shorter RFS and OS, which is in line with previous publications on the prognostic significance of SATB1 expression in several other major types of cancer." (PMID 25323550, 2014). "Therefore, immunohistochemistry should be the method of choice for assessment of the utility of SATB1 as a prognostic and treatment predictive biomarker in human cancer." (PMID 25323550, 2014). "To further examine whether SATB1565–574-specific CD8+ T cells were able to kill HLA-A*02+, SATB1-expressing cancer cells, we performed cytotoxicity assays." (PMID 23437226, 2013). "The recognition of HLA-A*02+ SATB1-expressing cancer cells was also tested." (PMID 23437226, 2013). "Positive signals for SATB1 mRNA localized as expected in the cytoplasm of cancer cells." (PMID 23326301, 2013). "Evidence from other studies shows SATB1 over-expression is a common phenomenon in a variety of neoplastic cells, and evidence also suggested SATB1 plays a broad role in the molecular regulation of cancer behavior which thus warrants further investigation." (PMID 23326301, 2013). "It should be noted that SATB1 is not only highly expressed in various types of malignant tumor, its expression was also detectable in thymocytes and progenitor cells including osteoblasts, the basal layer of the epidermis, amyloblasts, and embryonic stem cells." (PMID 23437226, 2013). "SATB1 has been shown to be abnormally expressed in various types of cancer." (PMID 23642278, 2013). "In addition, we also checked the expression of SATB1 protein among these cell lines, and found that all cancer cell lines expressed SATB1 protein except PC3 and Ovcar-3." (PMID 23437226, 2013). "Therefore, identification and development of more novel TAAs including SATB1 and peptide derivatives recognized by CTLs is definitely essential to facilitate the development of effective cancer vaccines." (PMID 23437226, 2013).
cancer (continued). "Importantly, SATB1565–574-specific T cells recognized and killed HLA-A*02+ SATB1+ cancer cells in an HLA-I-restricted manner." (PMID 23437226, 2013). "A premalignant gene expression signature that exhibits reduced ATM expression might be a prerequisite for SATB1 to induce cancer phenotypes." (PMID 23251624, 2012). "Special AT-rich sequence-binding protein-1 (SATB1) has been reported to be expressed in several human cancers and may have malignant potential." (PMID 22839214, 2012). "Moreover, these epigenetic contexts are maintained in cancer progenitors in which SATB1 has been identified as a factor related to Xist-mediated chromosome silencing." (PMID 24212802, 2011). "Moreover, the review discusses how the study of epigenetic context transitions in cancer cells allowed the identification of the special AT-rich binding protein SATB1 as a silencing factor." (PMID 24212802, 2011). "Furthermore, SATB1 is highly expressed in several cancer cell types." (PMID 37540226, 2023). "Additionally, well differentiated proliferating cancer cells might express SATB1 in contrast to benign tissue or poorly differentiated, aneuploid cancer cells." (PMID 34961766, 2021). "Interestingly, there was a reduction in both mRNA and protein levels of SATB1 in cancer." (PMID 33409278, 2020). "Finally, SATB1 was identified as a potential immune target for anti-cancer vaccines." (PMID 31450715, 2019). "And whether the lncSHRG/SATB1/HES6 axis works in other cancers remains to be elaborated." (PMID 29050307, 2017). "The intensity of cytoplasmic SATB1 expression was significantly higher in cancer cells as compared to its expression in enterocytes, whether all CRC (IRS 1.14 ± 0.21 vs. 0.2 ± 0.13; P < 0.01) or only paired samples (IRS 1.13 ± 0.33 vs. 0.2 ± 0.13; P < 0.05) were analyzed." (PMID 25874491, 2015). "Therefore, SATB1 becomes a potential target for cancer therapy." (PMID 24675979, 2014). "Among the remaining cases, SATB1 expression could be assessed in 106/108 (98.1%) primary PB-type carcinomas; 16 (15.1%) being denoted as positive and 90 (84.9%) as negative, and in 65/75 (86.7%) metastases; 11(16.9%) being denoted as positive and 54 (83.1%) as negative." (PMID 25323550, 2014). "Similarly to Satb1 and Hoxa1, Tmeff2 and Enpp2 are up regulated in carcinomas." (PMID 21054883, 2010). "Special AT-rich sequence-binding protein 1 (SATB1), a critical chromatin organizer, plays a pivotal role in cancer progression by regulating gene expression, chromatin remodeling, and cell signaling pathways." (PMID 40071088, 2025). "SATB1 modulates the expression of these genes at the transcriptional level, inhibiting CDH1 expression and promoting the conversion of cancer cells to a mesenchymal phenotype." (PMID 40071088, 2025). "Data indicates that SATB1 upregulates ALDH expression and promotes malignant potential by reprogramming energy metabolism in cancer cells." (PMID 38577616, 2024). "HBx can inhibit cancer cells from apoptosis by increasing the expression of the hepatoma upregulated protein (HURP) and special AT-rich sequence binding protein 1 (SATB1) gene, resulting in the overproduction of the anti-apoptotic protein surviving." (PMID 38464387, 2024). "SATB1 was the gene most frequently represented as a top NMF gene and was a signature gene for 12 cancer types." (PMID 37973839, 2023). "Within the SATB family, both SATB-1 and SATB-2 were investigated in cancer progression and are involved in human placenta development by promoting trophoblast stem cell renewal and inhibiting their differentiation." (PMID 34829454, 2021). "Nevertheless, Satb1 is known to be downregulated by Smad proteins under the influence of TGF-β, an immunosuppressive cytokine found to play a relevant role in cancer, resulting in elevated PD-1 levels." (PMID 33761971, 2021). "Studies have confirmed overexpression of both phospho SATB1 and protein kinase C (PKC) in glioblastoma, a deadly form of cancer that originates in the brain." (PMID 33409278, 2020).
cancer (continued). "The high expression of miR-888 also occurred more frequently in the cancers with strong survivin expression (P = 0.015) and the weak expression of AEG-1 (P = 0.003) and SATB1 (P = 0.036)." (PMID 33123477, 2020). "Our analyses focused on several key NMPs including SATB1/2, SAFB1/2, EZH2, SUZ12, BMI1, PCL3, RAE28, and CTCF, as these NMPs have been shown to be aberrantly expressed in cancers." (PMID 33124191, 2020). "It’s reported that SATB1 might cooperatively regulate expression of the anti-apoptotic BCL2 and pro-apoptotic NOXA genes to participate in disruption of apoptosis, which is a hallmark of cancer that reinforces tumorigenesis and resistance to cytotoxic cancer therapies." (PMID 31130823, 2019). "Previous studies have reported that several genes are directly targeted by miR-191 in human cancers including TET1, TIMP3, SATB1, and DIECR1." (PMID 31153371, 2019). "SATB1 is a global chromatin organizer that directly regulates the expression of ERRB2, MMP2, ABL1 and E-cadherin to act as a key regulator of cancer development." (PMID 24675979, 2014). "Besides, the peptide SATB1565–574 -HLA-I complexes on the surface of normal cells may be too low to reach the threshold for T cell scrutiny; while in cancer cells, over-expression of SATB1 results in increased presentation of the peptide on the cell surface for T cell recognition." (PMID 23437226, 2013). "The aim of the current study was to identify HLA-A*02 binding SATB1-derived epitopes recognized by CD8+ T cells in PBMCs of healthy subjects and cancer patients." (PMID 23437226, 2013). "Among the twelve SATB1-derived peptides, SATB1565–574 frequently induced peptide-specific T cell responses in PBMCs from both healthy donors and cancer patients." (PMID 23437226, 2013). "The present study confirms these findings in carcinomas of both the colon and the rectum, and more importantly analyzes the correlation of phenotypic and genotypic features of CRC related to SATB1 expression." (PMID 23326301, 2013). "Although SATB1 and SATB2 are homologous genes in which their amino acid sequence exhibits 60% homology, and SATB1 is a potential oncogene, the role of SATB2 in cancer is still unclear." (PMID 22815795, 2012). "We also overexpressed SATB1 in neoT and Ca1d of the MCF10A cancer progression series and examined the colony morphology in three dimensional (3D) cultures grown on top of Matrigel." (PMID 23251624, 2012). "Gene therapy approaches targeting SATB1 are rapidly advancing, with both viral and non-viral vectors showing promising results in preclinical cancer models." (PMID 40071088, 2025). "The molecular mechanism by which SATB1 drives cancer progression has not yet been fully elucidated, and concerns over the potential toxicity and off-target effects of SATB1 inhibition need to be addressed." (PMID 40071088, 2025). "SATB1 and FAK played an active function in the apoptotic cleavage of cellular proteins, similarly, miR-1224 accelerated the cell apoptosis via targeting SATB1 and FAK in cancer." (PMID 35494023, 2022). "These cancer cells can adapt by increasing their capacity to repair oxidative DNA damage in part through elevated expression of CUT domain proteins such as CUX1, CUX2, or SATB1." (PMID 34204734, 2021). "Moreover, our results showed that the expression of miR-888 was significantly higher in cancers with strong survivin and weak AEG-1 and SATB1 expression." (PMID 33123477, 2020). "Additionally, Ephrin receptors including EFNA4 belong to tyrosine kinase family, SATB1 and CRNDE have been shown to be elevated in CRC and other cancers, which lead to poor prognosis and metastasis." (PMID 32041340, 2020). "One of the proteins involved in cancer progression and EMT may be SATB1 (Special AT-Rich Binding Protein 1)—a chromatin organiser and a global transcriptional regulator." (PMID 31450715, 2019). "SATB1 is a chromatin modifier and it has also been shown to be a MDR gene in several cancer types." (PMID 25496125, 2014).
cancer (continued). "Different staining patterns for SATB1 and SATB2 were obtained on normal and cancer tissues." (PMID 25326863, 2014). "SATB1 was assessable in 63/65 (96.9%) primary I-type carcinomas; 15 (23.8%) being positive and 48 (76.2%) being negative, and in 26/30 (86.7%) metastases; 4 (15.4%) being positive and 22 (84.6%) being negative." (PMID 25323550, 2014). "Endogenous SATB1 expression levels (for both mRNA and protein) in cells from the MCF10A progression series were detectable, but significantly lower- 1/6th to 1/7th- than those in aggressive cancer cell lines." (PMID 23251624, 2012). "In contrast, SATB1 expression is either very low or undetectable in non-aggressive cancer cell lines and normal mammary epithelial cells." (PMID 23251624, 2012). "Furthermore, survival analyses of patients across various cancer types revealed that the expression of SATB family proteins, particularly SATB1 and SATB2, correlates with tissue-specific patterns and may significantly influence disease prognosis." (PMID 40689929, 2025). "Although the expression of SATB1 alone could be noted in some cancer cells in a few cases, it was not sufficient to obtain its prognostic value (data not shown)." (PMID 32612954, 2020). "Additionally, it has been shown that SATB1 may influence the EMT process and promote cancer metastasis." (PMID 31450715, 2019). "Positioning patterns for SP100 and SATB1 were similar in low and high T stage cancer specimens and could not be used to distinguish the different T stage group cancers from each other." (PMID 31681438, 2019). "After we screened the titles and abstracts, 21 papers were full-text reviewed and 11 articles including 3 meta-analyses or reviews, 2 studies explored SATB1 expression in other kind of cancer, 6 without sufficient data were further discarded in accordance with the exclusion standards." (PMID 29867574, 2018). "In summary, our work provides a better understanding of the physiological role of SATB1 in SCLC, SATB1 could regulate the invasion and migration of SCLC cells, this may provide important clues for more effective targeting of SCLC and other cancers with aberrant SATB1 activation." (PMID 23379909, 2013). "Consistent with Gleason score, the direction that SATB1 and LMNA repositioned did not aid in stratifying cancers by Gleason grade, but the direction of repositioning did correlate with Gleason grade for SP100 and TGFB3." (PMID 31681438, 2019). "Along this line, while some studies have suggested antagonistic effects of SATB1 and SATB2, it cannot be ruled out that SATB1 and SATB2 both increase chemotherapy sensitivity in the here examined types of cancer." (PMID 25323550, 2014). "No other genes were found commonly regulated by SATB1 between TE-1 cells and MDA-MB-231cells, suggesting that the downstream genes or functions of SATB1 in different cancer cells might be different." (PMID 28147311, 2017).
infection (9 papers, 2015 to 2025). The state of being infected such as from the introduction of a foreign agent such as serum, vaccine, antigenic substance or organism. "In contrast to myeloid cells, DCs, and ECs, we only detected few transcripts that are significantly elevated with infection in T cells including B2m, Satb1, Gm42418, Gimap6 in CD4+ T cells and Gm42418 in CD8+ T cells." (PMID 35789215, 2022). "Various repressors of apoptosis such as Ilf3, Zmym2, Satb1, Ccl21 and Scd were downregulated and expression levels of inducers of apoptosis such as Daxx, Oas1, Lcn2 and Gng2 were upregulated with V3000 infection at 24 h pi resulting in an overall activation of the apoptotic pathway." (PMID 28446152, 2017). "BETA predicted that SATB1 activity was significantly suppressed at 10 h post-infection with IAV." (PMID 26272204, 2015). "The infection of the monocytic THP-1 cell line with H37Rv of M. tuberculosis resulted in the increased methylation of histone H3K4me3 in the promoter regions of the DUSP4 gene and the gene for another immune regulatory protein special AT-rich sequence-binding protein 1 (SATB1)." (PMID 38139370, 2023). "Of these, CD44, KDM1B, FKBP4, TEF, SYT4, SATB1 and PLCD1 are reported to be involved in the inflammatory reaction; for the remaining ten genes, there have been no reports concerning inflammation or infection." (PMID 34046191, 2021).
adenocarcinoma (6 papers, 2013 to 2025). A common cancer characterized by the presence of malignant glandular cells. "The aim of our study was to examine longitudinal expression of SATB1 and its prognostic significance in adenocarcinomas of the esophagus, cardia, and stomach." (PMID 25326863, 2014). "In conclusion, we show that SATB1 is an independent prognostic biomarker in patients with radically resected adenocarcinomas of the upper gastrointestinal tract." (PMID 25326863, 2014). "In this study, expression of SATB1 was examined by immunohistochemistry on tissue microarrays prepared from tissue samples from 175 patients with adenocarcinoma of the esophagus, cardia, or stomach and containing normal tissue, intestinal metaplasia, primary tumors, and metastases." (PMID 25326863, 2014). "Expression of SATB1 was an independent predictor of a significantly shorter RFS and OS in pancreatobiliary type, but not in intestinal type adenocarcinomas." (PMID 25323550, 2014).
neurodevelopmental disorder (4 papers, 2022 to 2026). A behavioral and cognitive disorder with onset during the developmental period that involves impaired or aberrant development of intellectual, motor, or social functions. "We employed a rat model to investigate whether Satb1 dysfunction plays a critical role in the pathogenesis of neurodevelopmental disorders (NDDs)." (PMID 40571781, 2025).
colorectal (3 papers, 2012 to 2021). "Altogether, these data indicate an important role for SATB1 in colorectal carcinogenesis and suggest prognostically antagonistic effects of SATB1 and SATB2." (PMID 22935204, 2012).
gastrointestinal tract cancer (1 paper, 2017). "The combined HR was 1.79 (95% CI 1.34–2.41, p = 0.0003), which indicated that SATB1 overexpression is associated with a 1.79 fold increase in mortality in gastrointestinal tract cancer." (PMID 28430598, 2017).
hematological malignancies (1 paper, 2024). "The role and significance of SATB1 are opposite in solid tumors compared with hematological malignancies." (PMID 39195213, 2024).
neurodegenerative disease (1 paper, 2021). A disorder of the central nervous system characterized by gradual and progressive loss of neural tissue and neurologic function. "Satb1 is a risk factor for the development of neurodegenerative diseases, particularly Parkinson’s disease (PD)." (PMID 34073140, 2021).
SATB1 also shares sentences with these, for which no sentence is quoted: laryngeal squamous cell carcinoma (4 papers); infiltrating ductal breast carcinomas (3); renal cell carcinoma (3); Hodgkins lymphoma (2); squamous cell carcinoma (2); adenocarcinomas of pancreas (1); Alpha-thalassemia (1); Alzheimer disease (1); atopic-dermatitis (1); autism spectrum disorder (1); B-cell lymphoma (1); benign prostate hyperplasia (1); bladder urothelial carcinoma (1); bone metastasis (1); brain tumors (1); chronic mucus hypersecretion (1); colitis (1); colon adenocarcinoma (1); colorectal adenocarcinoma (1); COVID-19 (1); cutaneous leishmaniasis (1); diffuse large B-cell lymphoma (1); early-onset epilepsy (1); estrogen-receptor positive breast cancer (1); gastrointestinal neoplasms (1); genetic diseases (1); hepatitis B- (1); inflammation (1); liver cirrhosis (1); liver disease (1).
A further 16 diseases each share a sentence with SATB1 in 1 paper.